FAP (fibroblast activation protein alpha)
Diseases named in the same sentence as FAP in open-access papers (continued):
Sharing a sentence is not in itself a finding about the gene and the disease.
cancer (continued). "However, cancer cells that did not express FAP were not affected by FAP-targeted NIR-PIT and were not stained by PI." (PMID 33462372, 2021). "It has already been reported that compounds with high selectivity for FAP, such as FAPI-02, FAPI-04, and FAPI-46, are useful for diagnosis using labeled positron emitters (64Cu or 68 Ga) and treatment with labeled alpha or beta emitters (64Cu, 225Ac, 90Y, or 153Sm) for cancer, namely theranostics." (PMID 34420105, 2021). "Clinical trials failed to provide objective benefits from specific FAP inhibition, suggesting that blocking FAP functions may be almost irrelevant for cancer as a stand-alone therapy." (PMID 33562504, 2021). "In this primary culture, a unique transcription of the CXCL12 and FAP genes was observed; by pattern of gene expression, they corresponded to fibroblasts, and the SURV promoter of the cancer-specific gene Survivin (BIRC5) worked in it worse than in cancer cells." (PMID 33804861, 2021). "One partly supported hypothesis is that FAP, with its exo- and endo-dipeptidyl peptidase activity that is directed to certain ECM proteins, remodels the ECM for increased capability to support (cancer) cell growth." (PMID 32899119, 2020). "Notably, the same study demonstrated that a combined targeting of FAP+ CAFs and EPH receptor A2 (EphA2)+ cancer cells led to a nearly complete remission of the tumors, suggesting that CAF or PSC targeting can synergize with cancer-cell killing." (PMID 31108941, 2019). "Interestingly the BRAF-V600E positive TSA and carcinoma samples (both also containing mutation in the APC gene) clustered closely with SSP, but not FAP or other sample types." (PMID 29590112, 2018). "Cancer cells interact with MSCs, thereby leading to changes in MSCs' phenotype and inducing them to adopt features of CAFs such as the expression ofα-SMA, FSP1 (Fibroblast-Specific Protein), or FAP (Fibroblast-Activated Protein) or, depending on the cancer type, MSCs can further differentiate." (PMID 28473858, 2017). "TGF-β is a powerful factor for inducing FAP expression in NIH-3 T3 fibroblasts and, therefore, induction of FAP expression by TGF-β may be more suitable in terms of mimicking the environment of the stromal response to cancer in human PDAC tissue." (PMID 26330349, 2015). "However, the study did not indicate sibrotuzumab efficacy for the treatment of FAPα-positive cancer." (PMID 25593080, 2015). "FAP expression was positive in the matrix of cancer cells and negative in that of CAFs." (PMID 25189096, 2014). "Interestingly, we learned that the velocity of the migrating cancer cells is dependent on FAP expression regardless of its activity, whereas the latter is crucial for directionality." (PMID 21668992, 2011). "Additionally, the lack of differences in circulating FAP concentrations across cancer types and chemotherapy status suggests that other, yet unknown factors might regulate FAP homeostasis in these patients." (PMID 40690098, 2025). "In addition, fibroblasts (n = 1 068) were identified by COL1A1 and FAP, endothelial cells (n = 2 561) were positive for RAMP2 and CLDN5 expression, smooth muscle cells (n = 1 100) were defined by TAGLN and CNN1, and epithelial/cancer cells (n = 319) were labeled by KRT14 and KRT17." (PMID 40360503, 2025). "However, this could simply be due to cell immortalization rather than CAF function, as high FAP expression of Detroit551 was present even in the absence of cancer cells." (PMID 39384844, 2024). "We found that FAP expression was negatively correlated with CD8+ T cell infiltration in BRCA, CESC, HNSC, and SKCM, positively correlated with regulatory T cells in LIHC, PCPG, PRAD, and THCA, which suggested that FAP may contribute to the inhibitory immune microenvironment in these cancers." (PMID 39055892, 2024).
cancer (continued). "Furthermore, a high proportion of patients not expressing FAP in normal tissues had expression in cancer tissues, with almost one-quarter of cancers expressing this marker to a high degree, demonstrating that this target is highly specific in individual patients." (PMID 39335130, 2024). "Therefore, in addition to malignant tumors, CAFs accompanied with their FAP indicators may be present in nonmalignant situations that induce fibroblast activation." (PMID 35280710, 2022). "Moreover, in murine models of breast and colon cancer, the administration of a DNA-based vaccine targeting FAP induced the killing of CAF by CD8+ T cells and lead to a substantial increase in the uptake of chemotherapeutic agents by otherwise multi-drug-resistant cancer cells." (PMID 34094963, 2021). "In the field of nuclear medicine in particular, FAP appears to be a promising target due to its non-expression in normal fibroblasts and the stroma of benign epithelial tumors compared to its significantly high accumulation, mainly on the stromal compartments of a variety of malignant tumors." (PMID 34681246, 2021). "However, FAP expression is not cancer specific but activated fibroblasts in nonmalignant diseases may overexpress FAP." (PMID 34681850, 2021). "Interestingly, a combined targeting of FAP+ CAFs and EPH receptor A2 (EphA2)+ cancer cells led to a nearly complete remission of the tumors, suggesting that CAF-targeted approaches have the potential to supplement and synergize with conventional cancer-cell-targeted therapies." (PMID 31417869, 2019). "Numerous studies have explored FAP-targeted therapies and yield encouraging outcomes that underscore the potential of focusing on benign non-immune cells in the TME to combat cancer." (PMID 40248695, 2025). "Because the expression level of FAP on CAFs is not extremely high, a relatively large light dose was required to induce NIR-PIT targeting CAFs compared to NIR-PIT targeting cancer cells." (PMID 40361512, 2025). "FAP and MMP2 had the greatest percentage of patients with marker-present primary cancer tissue and marker-absent adjacent normal tissues (88.5% and 89.8%, respectively), indicating that these markers can specifically label cancer tissue." (PMID 39335130, 2024). "In contrast, the monospecific FAP-IL and mEnd-IL was taken up only by the HT1080-hFAP and the B16F10mCD105 cells, respectively, whereas LipQ was not taken up by any of the cancer cell lines." (PMID 32316521, 2020). "In subsequent studies, immune suppression by the FAP α+ CAFs was mediated by CXCL12, the chemokine that binds to cancer cells and excludes T cells by a mechanism that depends on signaling by the CXCL12 receptor, CXCR4." (PMID 26985769, 2016). "Nonetheless, FAP and LRRC15-targeted therapies that focus on CAFs alone may not be sufficient for cancer therapy." (PMID 41228205, 2025). "However, for FAP-TRT studies, a monoculture of CAFs would still not be adequate to study the complex aspects of indirect radiation of cancer cells after radiotracer binding to the CAFs." (PMID 39718718, 2024). "Importantly, inhibition of the Ki67+ cell population by SB‐431542 was restricted to the FAP+ cells, but not GFP+ cancer cells." (PMID 37330661, 2023). "Summarizing, the relatively low performance of [99mTc]Tc-iFAP in detecting LNm and Dm may be related to the molecular biology of cancer and the proportion of the enrichment of CAF-S1 FAP+, which is not the most abundant in metastatic lesions (LN or distant)." (PMID 35745648, 2022). "The transcripts of the FAP and CXCL12 genes were detected only in IVP-9TS primary culture of human fibroblasts, which is consistent with the literature data on their predominant expression in CAFs, but not in cancer cells." (PMID 33804861, 2021).
cancer (continued). "This study aimed to establish the spectrum of FAP expression across various cancers by immunohistochemistry and to explore whether 68Ga FAP inhibitor (FAPi)–46 PET biodistribution faithfully reflects FAP expression from resected cancer and non-cancer specimens." (PMID 34740953, 2022).
adenocarcinoma (21 papers, 2011 to 2025). A common cancer characterized by the presence of malignant glandular cells. "Conversely another study identified FAP+ CAFs and associated them with poor prognosis in adenocarcinoma, particularly in the presence of low CD8 T cell infiltration in the stroma." (PMID 38582812, 2024). "This is in line with immunohistochemistry findings revealing comparable FAP expression in adenocarcinoma and SCC." (PMID 40022163, 2025). "Current literature is focused on FAP expression in epithelial cancers and there is limited data on FAP expression in adenocarcinoma or other histologies." (PMID 38575990, 2024). "Of the tumors with secondary FAP-staining, 4/14 (28,6%) were adenocarcinomas and 71,5% (10/14) SCCs." (PMID 38575990, 2024). "In our cohort, more than half (53%) of patients had adenocarcinoma, with all primary tumors being FAP-positive." (PMID 38575990, 2024). "This study provides the first clinical evidence of the feasibility of treating different aggressive adenocarcinomas with 177Lu-labeled FAP-2286." (PMID 34168013, 2022). "This retrospective report provides the first—to our knowledge—evidence of the feasibility of theranostics in diverse advanced adenocarcinomas using the novel radiolabeled peptide 177Lu-FAP-2286." (PMID 34168013, 2022). "FAP expression was lower in CAFs from MuC and SrCC than in conventional adenocarcinoma (AdC)." (PMID 32428869, 2020). "However, we found that plasma samples from conventional adenocarcinoma patients had lower levels of the soluble fraction of FAP (sFAP) than those found in control subjects." (PMID 32428869, 2020). "Thus, FAP expression was significantly higher in tumors invading the visceral peritoneum or other adjacent organs (pT4) than in pT1-2 (p=0.002) and pT3 (p=0.009) adenocarcinomas." (PMID 32428869, 2020). "In cases of early adenocarcinoma, 18F-FDG PET/CT only detected three positive lesions, whereas FAP chemical staining positively identified 10 lesions, highlighting 68Ga-FAPI PET/CT’s potential superiority." (PMID 38779097, 2024). "In twelve early adenocarcinoma cases, only three lesions were positive for [18F]FDG on PET/CT, while ten lesions were immunohistochemically positive for FAP." (PMID 36428657, 2022). "Of the canonical changes noted, promoter (PR) DM loci with reciprocal changes in expression in adenocarcinomas included HBEGF, AGER, PTPRM, DPT, CST1, MELK; DM GB loci with concordant changes in expression included FOXM1, FERMT1, SLC7A5, and FAP genes." (PMID 26683690, 2015). "FAP expression showed opposite trends in the two cases: with one sample lower than PDAC (18#, pure ACC) and the other one higher than PDAC references (17#, mixed ACC-adenocarcinoma)." (PMID 39410042, 2024). "PERTINENT FINDINGS: In a series of 11 patients with diverse advanced adenocarcinomas, 177Lu-FAP-2286 was well tolerated, without any issues of urgent concern." (PMID 34168013, 2022). "The high expression of FAP-α in the adenocarcinoma group appears to be related to its high expression in nonsmoking women, a characteristic of the adenocarcinoma subtype." (PMID 35054034, 2022).
infection (13 papers, 2017 to 2025). The state of being infected such as from the introduction of a foreign agent such as serum, vaccine, antigenic substance or organism. "By targeting FAP, it reduces false positives caused by inflammation and infection and can effectively detect tumors with low metabolic activity." (PMID 39963103, 2025). "In this study, two‐antigen‐loaded DC vaccines are successfully built through infection with rAd encoding mouse FAP and human livin α, which have been reported as an efficient tool for transferring genes into DCs." (PMID 37773704, 2023). "FAP is upregulated in association with microbial stimulation and chronic inflammation, but its function in infection remains unknown." (PMID 28158223, 2017). "FAP is involved in infection response and inflammation and is expressed when cells are under pressure." (PMID 39452605, 2024). "Specific manifestations of infection, such as fibrosis, chronic granuloma, activated fibroblasts, and proliferation of small blood vessels, are also accompanied by FAP expression." (PMID 35725436, 2022). "FAP is secreted mainly by activated fibroblasts, which are abundant in the human body and are involved in infection response, inflammation, tumours and immunity." (PMID 35725436, 2022). "This phenomenon indicated that FAP was less expressed at the lesion site in the early stage of systemic inflammation and more expressed in the late stage, especially during infection." (PMID 35725436, 2022). "As such, understanding the role of FAP in infection is warranted to inform FAP targeting strategies in these patients." (PMID 28158223, 2017). "Intranasal infection with a sublethal dose of influenza virus H1N1/PR/8 induced marked upregulation of FAP expression in the lungs and lung-draining mediastinal lymph nodes of wildtype mice." (PMID 28158223, 2017). "However, the diagnostic efficacy of SUVmax was not satisfactory in 68 Ga-FAPI, and further study of the diagnostic criteria and basic research about the mechanism of FAP in infection and the expression site of FAP in infection is warranted." (PMID 35725436, 2022). "Furthermore, the role of FAP in infection remains largely uncharacterised." (PMID 28158223, 2017). "On day 7 post-infection, donor OT-I cells proliferated, and differentiated into CD44+CD62L- effector T cells to a similar extent in FAP knockout and WT mice." (PMID 28158223, 2017). "Of these, we selected 23 samples that were positive for at least three genotypes (named “Multiple-infection group”) and 27 samples negative to HPV through the same test, but positive when using FAP primers (named PGMY-HPV-neg group)." (PMID 32582561, 2020).
cardiovascular disease (11 papers, 2021 to 2025). "Although it has been previously studied in other cardiovascular diseases, to our knowledge, this is the first study to provide new information about plasma FAP levels in patients diagnosed with acute and chronic HF." (PMID 38297310, 2024). "Several pre-clinical studies investigated the role of FAP in cardiovascular diseases." (PMID 37762974, 2023). "The FAP-targeting radiotracer FAPI PET imaging may be used for specific imaging of incipient fibrosis in cardiovascular diseases." (PMID 37762974, 2023). "FAP, as a biomarker of activated fibroblasts, was targeted and visualised by FAPI PET to reflect and evaluate fibrosis in cardiovascular diseases." (PMID 37762974, 2023). "FAP is a specific biomarker for activated fibroblasts, rendering FAPI PET imaging the capability of visualising fibrosis in cardiovascular diseases." (PMID 37762974, 2023). "In cardiovascular diseases, FAP is expressed in activated rather than quiescent fibroblasts." (PMID 37762974, 2023). "While publications on FAP-specific PET for non-malignant indications are mostly limited to case reports and incidental findings, the first retrospective and prospective studies present promising results for IgG4-related as well as cardiovascular disease that warrant further research." (PMID 33606104, 2021).
gastrointestinal tumors (6 papers, 2022 to 2025). "First, we are the first to give a comprehensive illustration of FAP across gastrointestinal tumors using bioinformatics methods and then validate significant findings using experimental methods." (PMID 37325617, 2023). "The current research status of FAP-targeted imaging in gastrointestinal tumours is described in this review." (PMID 37608378, 2023). "In this regard, we further analyzed the expression of FAP at protein level in these gastrointestinal tumors using the National Cancer Institute’s CPTAC dataset." (PMID 37325617, 2023). "This systematic review and meta-analysis will synthesize all available evidence on the clinical implications of FAP overexpression in GI tumors." (PMID 37099374, 2023). "In recent years, several publications on FAP overexpression in gastrointestinal tumors have been published." (PMID 37099374, 2023). "Quantify FAP-expressing cells via 18F-FAPI-74 PET to assess tracer sensitivity in GI tumors." (PMID 40534854, 2025).
benign tumors (5 papers, 2014 to 2025). "The cases where FAP-specific PET has been used in patients with benign tumors hint at a low tracer uptake." (PMID 33606104, 2021). "The description of benign tumors on FAP-specific PET has been limited to occasional cases." (PMID 33606104, 2021).
breast (5 papers, 2021 to 2026). "Also, a high concentration of 99mTc-FAPI-04 was detected in the abdominal surgical scar and lung fibrosis tissue in 2 postoperative CRC patients, which occurred because fibroblasts in these tissues were activated along with the overexpression of FAP." (PMID 39376651, 2024).
metabolic disease (5 papers, 2016 to 2025). A congenital disorder (due to inherited enzyme abnormality) or acquired (due to failure of a metabolically important organ) disorder resulting from an abnormal metabolic process. "In this study, an association between increased FAP signal intensities, cardiovascular risk factors, and metabolic disease was reported." (PMID 37869159, 2023). "Here, we presented a novel FAP inhibitor, BR103354, and described its pharmacological activities as a potential therapeutic agent for the treatment of metabolic disorders." (PMID 33277568, 2020).
epithelial neoplasm (2 papers, 2015 to 2023). A benign or malignant neoplasm that arises from and is composed of epithelial cells. "Fibroblast activation protein α (FAPα) is a transmembrane serine protease and is highly expressed on CAFs present in >90% of human epithelial neoplasms." (PMID 25593080, 2015).
cardiac diseases (1 paper, 2021). "Furthermore, we analyzed fibroblast activation protein (FAP), which is upregulated in several cardiac diseases but is not expressed at a significant level in healthy tissue." (PMID 34638845, 2021).
gynecological tumors (1 paper, 2024). "However, FAP is overexpressed in more than 90% of epithelial tumors, including breast and gynecological tumors." (PMID 38505595, 2024).
hematologic cancers (1 paper, 2025). "Despite extensive studies on FAP in solid tumors, its role in hematologic cancers, particularly lymphoid malignancies, remains underexplored." (PMID 41373408, 2025).
hematologic malignancies (1 paper, 2025). "This connection underscores FAP as a potential target for therapeutic strategies aimed at overcoming chemoresistance in hematologic malignancies." (PMID 41373408, 2025).
inflammation (1 paper, 2014). Aberrant reaction of the microcirculation characterized by movement of fluid and leukocytes from the blood into extravascular tissues. "FAP was initially identified as being expressed in reactive fibroblasts for embryonic development or in chronic inflammation." (PMID 25126747, 2014).
skeletal disease (1 paper, 2024). "Moreover, FAPα levels were correlated with skeletal disease burden in patients with FD." (PMID 39273006, 2024).
FAP also shares sentences with these, for which no sentence is quoted: acute myocardial infarction (7 papers); neuropathy (6); autonomic dysfunction (3); chronic pancreatitis (3); colorectal adenoma (3); Hypertension (3); leiomyosarcoma (3); lymphoid neoplasm (3); neuroendocrine tumor (3); Alzheimer disease (2); amyloid disease (2); basal cell carcinoma (2); benign prostatic hyperplasia (2); cutaneous melanoma (2); endocervical adenocarcinoma (2); head and neck tumors (2); invasive lobular carcinoma (2); liver disease (2); mucinous neoplasm (2); mutyh-associated polyposis (2); myxofibrosarcoma (2); Pan (2); peripheral vascular disease (2); rhabdomyosarcoma (2); skin cancer (2); thymoma (2); uterine cancer (2); uveal melanoma (2); adenosquamous carcinoma (1); adrenocortical carcinoma (1).
A further 101 diseases each share a sentence with FAP in 1 paper.